CYBB (cytochrome b-245 beta chain)
Description:
Catalytic subunit of the phagocyte NADPH oxidase complex that mediates the transfer of electrons from cytosolic NADPH to O2 to produce the superoxide anion (O2(-)). In the activated complex, electrons are first transferred from NADPH to flavin adenine dinucleotide (FAD) and subsequently transferred via two heme molecules to molecular oxygen, producing superoxide through an outer-sphere reaction (Probable). Activation of the NADPH oxidase complex is initiated by the assembly of cytosolic subunits of the NADPH oxidase complex with the core NADPH oxidase complex to form a complex at the plasma membrane or phagosomal membrane. This activation process is initiated by phosphorylation dependent binding of the cytosolic NCF1/p47-phox subunit to the C-terminus of CYBA/p22-phox (By similarity). NADPH oxidase complex assembly is impaired through interaction with NRROS (By similarity).
Synonyms: NOX2; GP91-PHOX; GP91PHOX; p91-PHOX; AMCBX2; CGD; CGDX; GP91-1; IMD34
Tractability: Small molecule: a structure with a bound ligand is known; a high-quality ligand is known; it belongs to a druggable protein family. Antibody: UniProt places it where antibodies can reach, with high confidence; its Gene Ontology location is reachable by antibodies, with high confidence; UniProt predicts a signal peptide or a membrane-spanning region. PROTAC: UniProt records ubiquitination sites on it; ubiquitination databases record sites on it; its protein half-life has been measured; a small molecule that binds it is known.
Target class: Transmembrane 1-electron transfer carriers; Transporter
Gene: Protein-coding gene on chromosome X (37,780,018 to 37,816,994, forward strand). Ensembl gene ENSG00000165168.
Subcellular location: Cell membrane
Pathways (Reactome):
Signal Transduction: RAC1 GTPase cycle; RAC2 GTPase cycle; RAC3 GTPase cycle; RHO GTPases Activate NADPH Oxidases; VEGFA-VEGFR2 Pathway
Immune System: Cross-presentation of particulate exogenous antigens (phagosomes); Neutrophil degranulation; ROS and RNS production in phagocytes
Cellular responses to stimuli: Detoxification of Reactive Oxygen Species
Gene Ontology:
Molecular function: electron transfer activity; FAD binding; flavin adenine dinucleotide binding; heme binding; NADPH binding; protein binding; protein heterodimerization activity; superoxide-generating NAD(P)H oxidase activity; superoxide-generating NADPH oxidase activity; voltage-gated proton channel activity; NAD(P)H oxidase H2O2-forming activity; oxidoreductase activity
Biological process: innate immune response; respiratory burst; superoxide anion generation; superoxide metabolic process; defense response; inflammatory response; cellular response to cadmium ion; cellular response to ethanol; cellular response to hypoxia; cellular response to L-glutamine; hypoxia-inducible factor-1alpha signaling pathway; positive regulation of angiogenesis; positive regulation of tumor necrosis factor production; response to aldosterone; response to angiotensin; response to ethanol; response to nutrient; response to xenobiotic stimulus
Cellular component: NADPH oxidase complex; plasma membrane; endoplasmic reticulum membrane; phagocytic vesicle membrane; specific granule membrane; tertiary granule membrane; cytoplasm; dendrite; membrane; neuronal cell body; nuclear envelope; perinuclear endoplasmic reticulum; phagocytic vesicle
Homologues: Orthologues: chimpanzee CYBB (100% identical), macaque CYBB (97% identical), rat Cybb (93% identical), mouse Cybb (93% identical), dog CYBB (93% identical), guinea pig CYBB (91% identical), pig GP91-PHOX (88% identical), rabbit CYBB (86% identical), tropical clawed frog cybb (80% identical), zebrafish cybb (68% identical). Paralogues in human: NOX3 (59% identical), NOX1 (58% identical), NOX4 (39% identical), DUOX2 (31% identical), DUOX1 (31% identical), NOX5 (29% identical).
Diseases named in the same sentence as CYBB in open-access papers:
CYBB is named in the same sentence as 445 diseases in open-access papers, as found by Europe PMC text mining. Sharing a sentence is not in itself a finding about the gene and the disease. The quoted sentences say what the papers report.
chronic granulomatous disease (263 papers, 2006 to 2026). Chronic granulomatous disease (CGD) is a rare primary immunodeficiency, mainly affecting phagocytes, which is characterized by an increased susceptibility to severe and recurrent bacterial and fungal infections, along with the development of granulomas. "Subsequent genetic analysis identified a pathogenic mutation in the X-linked CYBB gene, confirming chronic granulomatous disease (CGD)." (PMID 42311883, 2026). "Six cases (37.5%) had chronic granulomatous disease (CGD) due to CYBB gene mutations, 2 cases (12.5%) had Mendelian susceptibility to mycobacterial disease (MSMD) due to IL12RB1 mutations, and 1 case (6.25%) had a FADD gene mutation." (PMID 40470261, 2025). "Case 3 was diagnosed with chronic granulomatous disease, harboring a variant of the CYBB gene (c.962 del T)." (PMID 40550072, 2025). "Mutation of the CYBB gene results in the most common form of the chronic granulomatous disease (CGD), which is X-linked recessive." (PMID 38956704, 2024). "Mutations in the NOX2/CYBB (previously gp91phox) nicotinamide adenine dinucleotide phosphate oxidase subunit are the commonest cause of chronic granulomatous disease, a disease characterized by infection susceptibility and an inflammatory phenotype." (PMID 38696730, 2024). "Chronic granulomatous disease, secondary to pathogenic variants in CYBB was the most common in these Mexican patients." (PMID 39836837, 2024). "Mutations in human CYBB have been previously associated to immune system dysfunction and can lead to chronic granulomatous disease." (PMID 36814923, 2023). "A pathogenic hemizygous synonymous variant NM_000397.4:c.483G > A (p.Lys161 =) was found in the CYBB gene related to Chronic granulomatous disease, X-linked (OMIM #306400) with XLR inheritance, that characterizes his Chronic granulomatous disease phenotype." (PMID 37592284, 2023). "Various subtypes of X-linked chronic granulomatous disease (XCGD) can arise from different types of mutations in the CYBB gene." (PMID 37533075, 2023). "Genetic defects in Nox2 (encoded by the X-linked CYBB gene) lead to chronic granulomatous disease (CGD), which is characterized by recurrent life-threatening bacterial and fungal infections." (PMID 36122532, 2022). "Twelve days later, WES reported c.121 locus T deletion mutation in the CYBB gene of the child, which is related to X-linked chronic granulomatous disease (X-CGD)." (PMID 35057749, 2022). "About 70% of patients with chronic granulomatous disease (CGD) have a mutation in the CYBB gene on the X chromosome." (PMID 33679872, 2020). "We also diagnosed two younger patients with diarrhoea as having chronic granulomatous disease (CYBB mutation) and hyper-IgM syndrome (CD40LG mutation)." (PMID 30001197, 2018). "Microarray analysis showed a 109 kb deletion of the CYBB gene consistent with X-linked Chronic Granulomatous disease confirming the diagnosis." (PMID 27034718, 2016). "Rare variants in CYBB (encoding gp91 phox ) are responsible for chronic granulomatous disease." (PMID 41816252, 2026). "However, only two of the patients with CYBB variants had X-linked chronic granulomatous disease associated with a missense variant." (PMID 41190063, 2025). "CYBB is one of the genes associated with Chronic Granulomatous Disease (CGD)." (PMID 40218181, 2025). "Chronic granulomatous disease (CGD) is an important feature of the CYBB mutation." (PMID 40656276, 2025). "Therefore, to show the general applicability of the CT strategy to every X chromosome genetic defect, we chose a mouse model of human chronic granulomatous disease due to mutations in the CYBB gene which maps to the X chromosome both in humans and mice." (PMID 38667281, 2024). "X-linked chronic granulomatous disease is a rare disease caused by mutations in the CYBB gene." (PMID 35945378, 2022).
chronic granulomatous disease (continued). "CYBB deficiency can lead to the disorder of reactive oxygen species (ROS) production, resulting in the disability of phagocytes to kill most pathogens, which is associated with the rare immune deficiency disorder, chronic granulomatous disease." (PMID 36193326, 2022). "Loss-of-function mutations in CYBB are known to cause chronic granulomatous disease (CGD)." (PMID 32081864, 2020). "Mutations in components of the NADPH oxidase complex—such as CYBB, encoding the catalytic subunit gp91phox—cause chronic granulomatous disease (CGD) in both humans and mice, leading to recurrent infections with catalase-positive bacteria and fungi." (PMID 40928289, 2025). "Mutations in the five structural genes (NCF1, NCF2, NCF4, CYBA, CYBB) are associated with chronic granulomatous disease (CGD), a condition characterized by impaired production of reactive oxygen species (ROS)." (PMID 37533075, 2023). "Through whole-exome sequencing, the child was ultimately diagnosed as X-linked chronic granulomatous disease (X-CGD) caused by CYBB gene mutation." (PMID 35057749, 2022). "X-Linked chronic granulomatous disease (X-CGD): Mutations in the Cytochrome B-245 Beta Chain (CYBB) gene results in defective production of antimicrobial reactive oxygen species." (PMID 34503562, 2021). "Here, we investigate the site-specific clustered regularly interspaced short palindromic repeat (CRISPR)-Cas9 system for correction of a point mutation in the CYBB gene that results in chronic granulomatous disease (CGD)." (PMID 26101162, 2015). "Mutations in CYBB resulting in defective gp91phox account for the majority of cases of Chronic Granulomatous Disease (CGD)." (PMID 21477322, 2011). "In X-linked chronic granulomatous disease, the insertion of the CYBB gene (encoding the gp91phox subunit of NADPH oxidase) into the AAVS1 site of patient-derived CD34+ HSCs restored gp91phox expression and NADPH oxidase activity in ex vivo–derived neutrophils." (PMID 41511364, 2026). "The best characterized genetic disease affecting neutrophil function is chronic granulomatous disease (CGD) which is caused by a defect in the genes encoding for components of the NOX2 complex, most prominently in the CYBB gene, which encodes for gp91phox." (PMID 38450755, 2024). "Another monogenic recessive disorder amenable to treatment with gene therapy is chronic granulomatous disease (CGD); the X-linked form of the disease results from mutations in the CYBB gene that encodes the gp91phox, the larger subunit of the oxidase flavocytochrome b558." (PMID 32204324, 2020). "In particular, Nox2 oxidase function deficiency in phagocytes due to genetic variants (CYBB, CYBA, NCF1, NCF2, and NCF4) has been recognized as a direct cause of chronic granulomatous disease (CGD), an inherited immune disorder." (PMID 29867559, 2018). "In humans, mutations in genes forming the Nox2 complex (CYBB, CYBA, NCF1,2,4) cause chronic granulomatous disease (CGD), a rare inherited immunodeficiency syndrome." (PMID 30274229, 2018). "A new study demonstrated ongoing processed pseudogene formation when the investigators identified an insertion of a partly processed TMF1 gene transcript into the cytochrome b-245, beta polypeptide (CYBB) gene of a chronic granulomatous disease patient." (PMID 27158268, 2016). "In addition, a hemizygous splice mutation in intron 5 of CYBB was linked to the concomitant occurrence of chronic granulomatous disease (CGD) with MTB." (PMID 25312698, 2015). "Chronic granulomatous disease, an immunodeficiency disorder in humans, is caused by a LINE-1 mediated insertion of a partially processed transcript into an intron of the CYBB gene, which encodes a cytochrome that is essential for phagocytosis by leukocytes." (PMID 26496357, 2015). "A similar splicing defect was described in a chronic granulomatous disease patient who carried a truncated L1 element in intron 5 of the CYBB gene." (PMID 22125493, 2011).
chronic granulomatous disease (continued). "CYBB deficiency has been associated with chronic granulomatous disease, whereas a lack of JAK3 can generate an increase in proinflammatory cytokines." (PMID 40006915, 2025). "MSMD-related NEMO and CYBB mutations are hypomorphic and do not always present with classic features of ectodermal dysplasia or chronic granulomatous disease." (PMID 40656276, 2025). "We described four male patients with chronic granulomatous disease: two with pathogenic variants in CYBB, one with CYBB and adjacent genes deleted, and one without p47phox expression." (PMID 39836837, 2024). "Chronic granulomatous Disease (CGD) is a rare innate immunodeficiency disorder caused by mutations in one of the six genes (CYBA, CYBB, NCF1, NCF2, NCF4, and CYBC1/EROS) encoding the superoxide-producing nicotinamide adenine dinucleotide phosphate (NADPH)—oxidase complex in phagocytes." (PMID 33746979, 2021). "Many loss-of-function alleles have been described for Nox2 NADPH oxidase subunits, with x-linked CYBB (gp91phox) being the most common cause of chronic granulomatous disease (CGD), a life-threatening primary immunodeficiency associated with recurrent bacterial and fungal infections." (PMID 26194095, 2015). "For example, LoF variants in CYBB, which encodes NOX2, a component of NADPH oxidase, typically cause chronic granulomatous disease (CGD) and a proportion of patients develop SLE." (PMID 38420886, 2024). "Pathogenic variants of CYBB [cytochrome b(-245), beta subunit; Mendelian Inheritance in Man [MIM] accession code, 300481] are known to cause "immunodeficiency 34, mycobacteriosis, X-linked" (IMD34, MIM#300645) and "chronic granulomatous disease, X-linked" (CGDX, MIM#306400)." (PMID 34268280, 2021). "Loss-of-function mutations in essential components of the NADPH oxidase including cytochrome b-245, α polypeptide CYBA, cytochrome b-245, β polypeptide (CYBB), and neutrophil cytosolic factor (NCF) 1 and 2 result in chronic granulomatous disease (CGD)." (PMID 35192551, 2022). "A consensus has been reached that the deficiency of CYBB leads to decreased NADPH oxidase activity in phagocytes, and neutrophils phagocytize bacteria but do not effectively kill bacteria, and that this might be the potential pathogenesis of chronic granulomatous disease." (PMID 34765659, 2021). "Studies of mutations causing human chronic granulomatous disease show that mutations in NCF1, CYBB, CYBA, or NCF2 lead to a complete lack of function of the NOX complex." (PMID 17897462, 2007). "When XK gene segment deletions are excessive, they may involve contiguous XK genes, such as the CYBB and RPGR genes, which could result in “Xp21 DNA microdeletion syndrome”, including XLRP, chronic granulomatous disease, Duchenne muscular dystrophy, and ornithine transcarbamylase deficiency (OTC)." (PMID 38343445, 2023). "Researching on mutations causing human chronic granulomatous disease showed that mutations in NCF1 and CYBB could result in a complete lack of function of the NOX2 complex." (PMID 37087463, 2023).
Hypertension (127 papers, 2011 to 2025). The presence of chronic increased pressure in the systemic arterial system. "CYBB, also known as NADPH-oxidase (NOX2) is known to be involved in angiotensin II-induced hypertension and endothelial dysfunction, as well as abundantly expressed in the endothelium." (PMID 36909892, 2023).
diabetes (117 papers, 2010 to 2026). "Significantly overexpressed CYBB in GK stain is a critical contributor to the microvascular complications associated with diabetes." (PMID 21689475, 2011).
atherosclerosis (81 papers, 2008 to 2025). A disease characterized by the build-up of fatty material and calcium deposition in the arterial wall resulting in partial or complete occlusion of the arterial lumen. "The expression of the genes CYBB, FCER1G, TYROBP, IL10RA, and CSF1R is increased in both ANCA-associated vasculitis and atherosclerosis." (PMID 39702436, 2024). "The immune-associated genes in both atherosclerosis and osteoporosis from WGCNA mainly included TREM1, CYBB, CCR1, CD83, CD52, IL7R, and THBS1." (PMID 35937806, 2022). "CYBB, HMOX1, IL1B, TYROBP, and CSF1R are key genes associated with ferroptosis, a form of cell death triggered by lipid metabolism abnormalities in the context of atherosclerosis." (PMID 40895546, 2025). "Functional analysis of CAG and atherosclerosis revealed a high enrichment of reactive oxygen pathways, which may be mediated through CYBB." (PMID 38640295, 2024). "According to the findings of our research, the genes CYBB, FCER1G, TYROBP, IL10RA, and CSF1R could represent relevant targets for the study and development of therapeutic strategies aimed at ANCA-associated vasculitis and atherosclerosis." (PMID 39702436, 2024).
cardiac hypertrophy (55 papers, 2010 to 2025). "Cytochrome b-245 beta chain gene is part of cytochrome b-245, which is essential for microbicidal oxidase development in phagocytic cells that plays critical roles in the pathogenesis of coronary artery disease; it is also associated with ventricular hypertrophy and arrhythmia." (PMID 36035865, 2022).
Sepsis (55 papers, 2012 to 2026). Sepsis is defined as life-threatening organ dysfunction caused by a dysregulated host response to infection. "Since CYBB is mainly expressed in the lungs in humans, we focused on the changes in lung injury caused by sepsis." (PMID 37901228, 2023). "Several previous studies have linked FCAR and CYBB to sepsis." (PMID 37901228, 2023). "This study is the first to reveal potential activation of the entotic pathway in sepsis patients and identifies two key genes associated with this process: BECN1 and CYBB." (PMID 41346577, 2025). "Inhibition of CYBB can also inhibit microglial activation and improve cognitive impairment after sepsis, as well as promoting sepsis myocardial injury through the ERK1/2-TNFα pathway." (PMID 37901228, 2023). "Together, we illustrated by machine learning that CYBB and FCAR were significantly associated with sepsis-related mortality." (PMID 37901228, 2023). "Our findings implied that higher CYBB and FCAR expression were significantly and positively associated with higher mortality rates in the sepsis group." (PMID 37901228, 2023). "In particular, CYBB and FCAR were significantly associated with survival in patients with sepsis, and both genes were validated using animal experiments and analysis of clinical specimens." (PMID 37901228, 2023). "Nevertheless, the mean level of CYBB expression in the sepsis group was higher than that in the healthy group." (PMID 37901228, 2023). "CYBB (also known as NOX2), a central component of the NADPH oxidase complex, promotes ROS production and has been shown to be upregulated in sepsis, facilitating NETosis formation via oxidative stress." (PMID 41346577, 2025). "CYBB and FCAR levels were significantly elevated in sepsis patients compared with the healthy group." (PMID 37901228, 2023). "Bioinformatics analysis showed that CYBB and FCAR levels are related to the survival of patients with sepsis." (PMID 37901228, 2023). "Notably, the expression patterns of core PCD-related genes in this cohort were highly consistent with those observed in the discovery datasets, with genes such as CYBB, GCLM, MAP1LC3B, NCKAP1, and PGD markedly upregulated in sepsis patients." (PMID 41346577, 2025). "Of these, CYBB and FCAR were independent predictors of poor survival in patients with sepsis." (PMID 37901228, 2023). "CYBB and FCAR may be reliable biomarkers of survival in patients with sepsis, as well as potential targets for sepsis treatment." (PMID 37901228, 2023). "The results indicated that 8 genes (MAPK14, MAPK8, TLR4, MAP3K5, CYBB, DUSP1, MAPK1 and ATM) might be closely related to the occurrence of sepsis." (PMID 36117534, 2022).